PORCN (porcupine O-acyltransferase)
Description:
Protein-serine O-palmitoleoyltransferase that acts as a key regulator of the Wnt signaling pathway by mediating the attachment of palmitoleate, a 16-carbon monounsaturated fatty acid (C16:1(9Z)), to Wnt proteins. Serine palmitoleoylation of WNT proteins is required for efficient binding to frizzled receptors.
Synonyms: MG61; PORC; PPN; por; DHOF; FODH
Tractability: Small molecule: a drug acting on it is in phase 2 or 3 trials; a structure with a bound ligand is known; a high-quality ligand is known; it belongs to a druggable protein family. Antibody: UniProt predicts a signal peptide or a membrane-spanning region. PROTAC: ubiquitination databases record sites on it; its protein half-life has been measured; a small molecule that binds it is known.
Target class: Enzyme; Transferase
Gene: Protein-coding gene on chromosome X (48,508,574 to 48,520,814, forward strand). Ensembl gene ENSG00000102312.
Subcellular location: Endoplasmic reticulum membrane
Subcellular location (Human Protein Atlas): Vesicles
Pathways (Reactome):
Disease: LGK974 inhibits PORCN
Signal Transduction: WNT ligand biogenesis and trafficking
Gene Ontology:
Molecular function: palmitoleoyltransferase activity; Wnt-protein binding
Biological process: lipid modification; protein lipidation; protein palmitoleylation; Wnt protein secretion; Wnt signaling pathway
Cellular component: endoplasmic reticulum; endoplasmic reticulum membrane; membrane
Gene-disease validity (ClinGen):
ClinGen rates the evidence that PORCN causes each of these diseases.
focal dermal hypoplasia (X-linked): Definitive. A syndrome characterized by a polymorphic cutaneous disorder and highly variable anomalies affecting the eyes, teeth, skeleton and the central nervous, urinary, gastrointestinal and cardiovascular systems.
Homologues: Orthologues: chimpanzee PORCN (99% identical), macaque PORCN (99% identical), rabbit PORCN (98% identical), pig PORCN (98% identical), mouse Porcn (97% identical), rat Porcn (97% identical), guinea pig PORCN (96% identical), dog PORCN (85% identical), zebrafish porcn (66% identical), zebrafish porcnl (64% identical), tropical clawed frog porcn (55% identical), Drosophila melanogaster por (34% identical), and 1 more. Paralogues in human: MBOAT1 (20% identical), MBOAT2 (18% identical), LPCAT3 (18% identical), MBOAT7 (17% identical), MBOAT4 (15% identical).
Diseases named in the same sentence as PORCN in open-access papers:
PORCN is named in the same sentence as 52 diseases in open-access papers, as found by Europe PMC text mining. Sharing a sentence is not in itself a finding about the gene and the disease. The quoted sentences say what the papers report.
Goltz syndrome (18 papers, 2012 to 2026). "PORCN variants cause an X-linked dominant focal dermal hypoplasia (Goltz syndrome), which is usually male-lethal, while females are variably affected." (PMID 41256177, 2025). "Goltz syndrome (GS) is a X-linked disorder defined by defects of mesodermal- and ectodermal-derived structures and caused by PORCN mutations." (PMID 35101074, 2022). "Focal dermal hypoplasia or Goltz syndrome is caused by variants in porcupine O-acyltransferase (PORCN) gene." (PMID 34198563, 2021). "OC15 carried a nonsense mutation (p.Arg95*) in PORCN, which is a gene responsible for Goltz-Gorlin syndrome, while OC15b carried an indel mutation in ZIC2 leading to the substitution of three residues by a proline (p.His404_Ser406delinsPro)." (PMID 33557041, 2021). "Mutations in human PORCN cause FDH (Goltz Syndrome, OMIM#305600), an X-linked dominant disorder characterized by dysplasias in ecto-mesodermal tissues." (PMID 24223895, 2013). "Here, we report a novel mosaic mutation in the PORCN gene in a male Goltz syndrome patient." (PMID 30455901, 2018). "Also known as Goltz syndrome or Goltz-Gorlin syndrome, it has since been established to be an X-linked dominant disorder caused by mutations in the PORCN gene." (PMID 28626639, 2017). "However, the effect of PORCN inhibition we observe suggests that the focal dermal hypoplasia observed in Goltz syndrome, caused by mutation of PORCN (OMIM 305600), may be contributed to by locally dysregulated mesenchymal cell movement." (PMID 37747910, 2023). "Myelomeningocele has been documented in a person with focal dermal hypoplasia (FDH), a rare congenital disorder associated with mutations in PORCN." (PMID 32970752, 2020). "PORCN is located on the X-chromosome, and heterozygous loss-of-function mutations can cause focal dermal hypoplasia (FDH) also known as Goltz syndrome in female patients." (PMID 32328030, 2020). "An extensive number of mutations throughout the coding region and large gene rearrangements of PORCN have been identified in focal dermal hypoplasia or Goltz–Gorlin syndrome, which includes orofacial clefts." (PMID 30760477, 2019). "Inherited and post-zygotic mutations in PORCN, an X-linked gene, cause FDH (focal dermal hypoplasia, also known as Goltz syndrome), a disease that predominantly affects females." (PMID 25208913, 2014). "Goltz syndrome caused by mutations in PORCN is rarely reported in males which leads to the suspicion that non-mosaic Goltz syndrome is embryonically lethal for males." (PMID 32328030, 2020).
breast cancer (8 papers, 2012 to 2025). A primary or metastatic malignant neoplasm involving the breast. "Inhibition of PORCN was shown to prevent the growth of mammary tumors in mice with little toxicity to the mouse." (PMID 37250116, 2023). "LGK-974 (PORCN inhibitor) and pictilisib treatment synergistically reduced ER− human breast cancer cell proliferation." (PMID 37471270, 2023). "LGK-974 (PORCN inhibitor) and buparlisib treatment synergistically reduced the viability and xenograft tumor growth of ER− human breast cancer cells." (PMID 37471270, 2023). "Buparlisib treatment increased PORCN, Wnt ligand and receptor mRNA expression in ER− human breast cancer cells." (PMID 37471270, 2023). "WNT secretion is also targeted by some inhibitors like the inhibitor IWP-2 for treatment of cancers, especially pancreatic cancers with RNF43 mutations, whereas PORCN inhibitors WNT974 and ETC-159 are applicable to prevent mammary tumors and cancer stem cells." (PMID 35965500, 2022). "To test if PORCN was important for breast cancer cell proliferation we first assessed its expression in a panel of breast cancer cell lines." (PMID 22509316, 2012). "LGK-974 (PORCN inhibitor) rescued enhanced proliferation of INPP4B-overexpressing PIK3CA-mutant ER+ human breast cancer cells.Pyrvinium (CK1α inhibitor) reduced viability and 3D spheroid growth of INPP4B-overexpressing PIK3CA-mutant ER+ human breast cancer cells." (PMID 37471270, 2023). "LGK-974 is a PORCN inhibitor that prevents Wnt ligand acylation and secretion and successfully reduced Wnt signaling in phase I clinical trials in a range of solid tumors including breast cancer." (PMID 36612130, 2022). "A separate study has demonstrated the therapeutic potential of Wnt‐c59, a PORCN inhibitor with similar potency to CGX1321, when administered orally over a short intervention period (i.e., 2 weeks) in a mouse model of mammary cancer." (PMID 39743495, 2025). "Another PORCN inhibitor, LGK974, was found to prevent Wnt signaling in murine and rat mechanistic breast cancer models and human head and neck cell model (HN30)." (PMID 37250116, 2023). "The porcupine O-acyltransferase (PORCN) inhibitors LGK-974 or IWP-2, which prevent Wnt ligand secretion, rescued the increased proliferation of INPP4B-overexpressing ER+ breast cancer cells." (PMID 37471270, 2023). "Pictilisib (strong PI3Kα/δ, modest PI3Kβ/γ inhibitor) treatment had little effect on the proliferation of ER− breast cancer cells, whereas combined pictilisib and LGK-974 (PORCN inhibitor) treatment synergistically reduced ER− breast cancer cell proliferation." (PMID 37471270, 2023). "In the breast cancer models driven by MMTV-Wnt1, the application of the PORCN inhibitor LGK974 or Wnt-C59 showed a strong tumor-suppressing effect." (PMID 32104684, 2020). "Furthermore, other PORCN inhibitors such as Wnt-C59 and ETC 159 have also been studied for their effects against mammary tumors in MMTV-Wnt1 transgenic mice." (PMID 27570510, 2016). "While we found a decrease in growth in a number of breast cancer cell lines, PORCN knockdown did not result in apoptosis or a shift in cell cycle distribution in any of the cancer lines tested (and data not shown)." (PMID 22509316, 2012). "Because Wnt signaling can activate both β-catenin dependent and β-catenin-independent pathways, we tested if PORCN knockdown affected the proliferation and survival of these human breast cancer cell lines even in the absence of detectable endogenous β-catenin signaling." (PMID 22509316, 2012).
pancreatic cancer (7 papers, 2016 to 2023). "PORCN inhibitor–resistant RNF43-mutant pancreatic cancer cell lines harbor loss-of-function genetic alterations in EP300." (PMID 35536676, 2022). "Taken together, these results indicate that downregulation of GATA6 mediated the PORCN inhibitor resistance caused by p300 loss in RNF43-mutant pancreatic cancers." (PMID 35536676, 2022). "We then asked whether the mutation of these Wnt pathway genes was responsible for PORCN inhibitor resistance in RNF43-mutant pancreatic cancers." (PMID 35536676, 2022). "Similar effects have been observed in other cancers such as pancreatic cancer, where combined ETC-159 (PORCN inhibitor) and pictilisib treatment synergistically reduced pancreatic cancer cell proliferation and xenograft tumor growth." (PMID 37471270, 2023). "This identifies a more general role for a p300/GATA6 axis in cancer and suggests that p300 and GATA6 status can be used to stratify RNF43-mutant pancreatic cancer patients to maximize the clinical benefits of PORCN inhibitors." (PMID 35536676, 2022). "Supporting its importance, we found that EP300 is inactivated in the preexisting PORCN inhibitor–resistant RNF43-mutant pancreatic cancer cell lines." (PMID 35536676, 2022). "Our previous study showed that a relatively small scale CRISPR library can be faithfully represented in subcutaneous xenografts of HPAF-II cells, a PORCN inhibitor–sensitive RNF43-mutant pancreatic cancer model." (PMID 35536676, 2022). "We found that EP300 is silenced due to genetic alterations in all the existing RNF43-mutant pancreatic cancer cell lines that are resistant to PORCN inhibitors." (PMID 35536676, 2022). "Accordingly, PORCN inhibitor LGK974 blocked pancreatic tumor development and prolonged the survival of Rnf43−/−; KrasG12D mice." (PMID 35229994, 2022). "RNF43-mutant pancreatic cancers are dependent on Wnt production, and pharmacologic blockade of the pathway, e.g., by PORCN inhibitors, leads to tumor differentiation." (PMID 35536676, 2022). "To elucidate potential mechanisms, we performed in vivo CRISPR screens in PORCN inhibitor–sensitive RNF43-mutant pancreatic cancer xenografts." (PMID 35536676, 2022). "This is similar to the tumor differentiation observed in other PORCN inhibitor–sensitive RNF43-mutant pancreatic tumors following Wnt inhibition." (PMID 35536676, 2022). "Consistent with this, PORCN inhibition decreased MYBL2 protein abundance in HPAF‐II pancreatic tumors." (PMID 33660437, 2021). "Using an orthotopic Wnt-addicted pancreatic cancer model treated with a potent and effective PORCN inhibitor, we identified 1503 lncRNAs regulated by Wnt signaling in vivo." (PMID 33092630, 2020). "Intrinsic resistance to PORCN inhibitors in some RNF43-mutant pancreatic cancers." (PMID 35536676, 2022). "Moreover, in preclinical studies, several pancreatic cancer cell lines with confirmed RNF43 inactivation were identified that were resistant to PORCN inhibition in cell culture." (PMID 35536676, 2022). "Small molecule PORCN inhibitors that block the biogenesis of Wnt ligands as well as antibodies that block Wnt function have been shown to inhibit tumor growth in preclinical models of RNF43-mutant pancreatic cancers, and several have advanced into clinical trials." (PMID 35536676, 2022). "However, these negative regulators of the Wnt/β-catenin pathway were neither mutated nor silenced in the existing PORCN inhibitor–resistant RNF43-mutant pancreatic cancer cell lines based on genome, exome, and/or transcriptome sequencing results from public databases." (PMID 35536676, 2022). "Here, to identify mechanisms that confer resistance to upstream Wnt pathway inhibitors in RNF43-mutant pancreatic cancers, we performed in vivo CRISPR screens during PORCN inhibitor therapy in mice bearing RNF43-mutant pancreatic tumor xenografts." (PMID 35536676, 2022).
pancreatic cancer (continued). "Since Wnt‐addicted cells are substantially more sensitive to PORCN inhibitors when grown in suspension, the screen was performed in the Wnt‐addicted RNF43‐mutant pancreatic cancer cell line HPAF‐II using soft agar colony formation as the readout." (PMID 33660437, 2021).
colorectal cancer (3 papers, 2016 to 2023). A primary or metastatic malignant neoplasm that affects the colon or rectum. "RNF43 loss-of-function mutations are often detected in MSI-type colorectal cancer, and PORCN inhibitor, which can inhibit ligand-mediated activation of the Wnt/β-catenin cascade, can effectively inhibit the progression of RNF43-mutant cell-derived PDX colorectal cancer in vivo." (PMID 37848933, 2023). "To test whether PORCN inhibition causes a decrease in HR and FA genes in additional Wnt‐addicted cancer models, we examined RNA‐seq data from a colorectal cancer patient‐derived xenograft (CRC PDX) with a RSPO3 translocation that was treated with ETC‐159." (PMID 33660437, 2021).
lung carcinoma (3 papers, 2012 to 2022). "Previous studies suggested that CD133 marks an aggressive cell population in lung cancer that may be explained by the differential ability of tumor cell subpopulations to form a PORCN+ microniche." (PMID 34249925, 2021). "RNAi-mediated knockdown of PORCN has been reported to cause apoptosis in human lung cancer cells, although this finding could not be independently reproduced." (PMID 22509316, 2012).
clear cell renal cell carcinoma (2 papers, 2020). "Although porcupine (PORCN) as a palmitoyltransferase plays a crucial role in the activation and secretion of Wnt proteins and affects the activity of the Wnt signaling pathway, little is known about the role of PORCN in clear cell renal cell carcinoma (ccRCC)." (PMID 32104684, 2020). "In renal clear cell carcinoma, when LGK974 was used to inhibit the expression of PORCN, the activity of the Wnt/β-catenin pathway was downregulated and proliferation, migration, and invasion were inhibited." (PMID 32908919, 2020).
Ewing sarcoma (2 papers, 2021 to 2025). A small round cell tumor that lacks morphologic, immunohistochemical, and electron microscopic evidence of neuroectodermal differentiation. "Therapeutically, inhibition of the WNT/β-catenin pathway in Ewing sarcoma with the PORCN inhibitor, WNT974, decreases metastatic Ewing sarcoma in a mouse model but does not affect overall survival." (PMID 40983796, 2025).
Fanconi anemia (2 papers, 2021 to 2025). Fanconi anemia (FA) is a hereditary DNA repair disorder characterized by progressive pancytopenia with bone marrow failure, variable congenital malformations and predisposition to develop hematological or solid tumors. "Mechanistically, we find that multiple genes in the homologous recombination and Fanconi anemia repair pathways, including BRCA1, FANCD2, and RAD51, are dependent on Wnt/β‐catenin signaling in Wnt‐high cancers, and treatment with a PORCN inhibitor creates a BRCA‐like state." (PMID 33660437, 2021).
fibrosarcoma (2 papers, 2012 to 2024). A malignant mesenchymal fibroblastic neoplasm affecting the soft tissue and bone. "We expressed WNT4 or WNT3A fused to C-terminal BirA biotin ligase in HT1080 WT and porcupine O-acetyltransferase (PORCN)-knockout (PKO) cells (Wnt-responsive fibrosarcoma cell line), and ILC cell line MDA MB 134VI (MM134)." (PMID 38112643, 2024). "Knockdown of PORCN did not affect the proliferation of HEK 293 cells, HT1080 fibrosarcoma cells, non-transformed HMECs, or BJ foreskin fibroblast cell lines regardless of transformation status." (PMID 22509316, 2012).
gastric cancer (2 papers, 2016 to 2020). A primary or metastatic malignant neoplasm involving the stomach. "In gastric cancer and glioblastoma, PORCN inhibitors significantly inhibit tumor cell proliferation and migration and induce apoptosis." (PMID 32104684, 2020). "Low level of DIM promoted gastric cancer progression by inducing the PORCN-dependent secretion of Wnt4 and the activation of β-catenin signaling." (PMID 26918831, 2016). "The interference with PORCN expression reversed low level of DIM-induced gastric cancer progression, indicating that the autorcine of active Wnt is essential for this process." (PMID 26918831, 2016).
Klinefelter syndrome (2 papers, 2025 to 2026). A sex chromosome disorder caused by the presence of an extra X chromosome in the male karyotype. "This provides grounds for the hypothesis that the man does not have a typical XY karyotype, but most likely has Klinefelter syndrome (47,XXY), which would explain both the presence of an additional X-chromosomal allele and the possibility of survival with a PORCN mutation." (PMID 41450356, 2025).
lung adenocarcinoma (2 papers, 2020 to 2021). A carcinoma that arises from the lung and is characterized by the presence of malignant glandular epithelial cells. "Although nearly all cells in pancreatic ductal (PD) and pancreatic ductal adenocarcinoma (PDAC) samples expressed porcupine (PORCN), an enzyme critical for Wnt secretion, only a subpopulation of lung bronchiolar (NL) and lung adenocarcinoma (LUAD) organoid cells produced active Wnt." (PMID 34249925, 2021). "In lung adenocarcinoma (LUAD), after using the PORCN inhibitor LGK974 or small interfering RNA, the target genes of the Wnt pathway was downregulated, the activity of Wnt pathway was decreased, and the growth of tumor was significantly inhibited." (PMID 32104684, 2020).
non-small cell lung carcinoma (2 papers, 2012 to 2023). A group of at least three distinct histological types of lung cancer, including non-small cell squamous cell carcinoma, adenocarcinoma, and large cell carcinoma. "A recent paper investigating PORCN in Non Small Cell Lung Carcinoma illustrated that loss of PORCN downregulates S100P at the mRNA and protein levels in a β-catenin independent manner, similar to what we have shown for APEH." (PMID 22509316, 2012). "In non-small cell lung cancer (NSCLC), Wnt ligands (Wnt1, Wnt2, Wnt3, and Wnt5a) and other signaling modules (FZD8, PORCN, and TCF-4) are overexpressed." (PMID 37190019, 2023).
ovarian carcinoma (2 papers, 2020 to 2022). A malignant neoplasm originating from the surface ovarian epithelium. "For example, dasatinib is used in the activation of EphA3 via mediating role of the ABL1 protein kinase domain in lymphoblastic leukemia, and PORCN is considered suitable for the palmitoleation of mammalian Wnts to treat ovarian cancer." (PMID 36139498, 2022). "Next, we asked if targeting the Wnt pathway via use of a PORCN inhibitor would reverse the phenomena of T cell exclusion and promote a hot TME in a clinically relevant pre-clinical murine model of ovarian cancer." (PMID 32213921, 2020). "We used CGX1321, an inhibitor to the porcupine (PORCN) enzyme that is necessary for secretion of WNT ligand, in mice with established ID8 tumors, a murine ovarian cancer cell line." (PMID 32213921, 2020).
cardiac hypertrophy (1 paper, 2025). "Furthermore, Porcupine (PORCN) inhibitors, which negatively regulate Wnt signaling, have shown promising results in improving cardiac function and reducing cardiac hypertrophy and/or fibrosis." (PMID 39743495, 2025).